KRT7 (keratin 7)
Description:
Blocks interferon-dependent interphase and stimulates DNA synthesis in cells. Involved in the translational regulation of the human papillomavirus type 16 E7 mRNA (HPV16 E7).
Synonyms: CK-7; K7; SCL; CK7; K2C7
Tractability: Small molecule: a structure with a bound ligand is known. PROTAC: UniProt records ubiquitination sites on it; ubiquitination databases record sites on it; its protein half-life has been measured.
Gene: Protein-coding gene on chromosome 12 (52,232,520 to 52,252,186, forward strand). Ensembl gene ENSG00000135480.
Subcellular location: Cytoplasm
Subcellular location (Human Protein Atlas): Cytosol; Intermediate filaments
Pathways (Reactome):
Developmental Biology: Developmental Lineage of Pancreatic Ductal Cells; Formation of the cornified envelope; Keratinization
Gene Ontology:
Molecular function: protein binding; structural constituent of skin epidermis
Biological process: intermediate filament organization; keratinization
Cellular component: cytoplasm; cytosol; extracellular exosome; nucleus; intermediate filament; keratin filament
Genetic constraint (gnomAD): Loss-of-function variants: 45 observed, 39.54 expected, observed/expected ratio (o/e) 1.14, 90% interval 0.89 to 1.46. The upper end of that interval is the gene's LOEUF score, 1.46, which puts it in group 6 of 6, group 1 being the genes least tolerant of losing a copy. Missense variants: 557 observed, 590.02 expected, observed/expected ratio (o/e) 0.94, 90% interval 0.88 to 1.01. Synonymous variants: 256 observed, 249.18 expected, observed/expected ratio (o/e) 1.03, 90% interval 0.93 to 1.14.
Homologues: Orthologues: chimpanzee KRT7 (99% identical), macaque KRT7 (97% identical), pig KRT7 (85% identical), mouse Krt7 (81% identical), rat Krt7 (80% identical), guinea pig KRT7 (79% identical), rabbit KRT7 (61% identical). Paralogues in human: KRT5 (65% identical), KRT6A (64% identical), KRT6B (64% identical), KRT75 (64% identical), KRT6C (64% identical), KRT76 (59% identical), KRT3 (59% identical), KRT79 (58% identical), KRT8 (58% identical), KRT4 (57% identical), KRT73 (56% identical), KRT72 (56% identical), and 56 more.
Diseases named in the same sentence as KRT7 in open-access papers:
KRT7 is named in the same sentence as 421 diseases in open-access papers, as found by Europe PMC text mining. Sharing a sentence is not in itself a finding about the gene and the disease. The quoted sentences say what the papers report.
breast carcinoma (111 papers, 2006 to 2026). "KRT7, conversely, has consistently been associated with cancer progression in various tumors, including breast cancer, colon cancer, pancreatic cancer, and gastric cancer 25-28." (PMID 38495507, 2024). "As for the functions of proteins encoded by signature genes, KRT7 is found to be tightly linked to cancer metastasis in colorectal cancer and breast cancer." (PMID 34993203, 2021). "When we classified patients by breast cancer subtypes, we observed that higher KRT7 levels were associated with the poorest outcome in basal and HER2+ subtypes but not in the more differentiated luminal A and luminal B subtypes." (PMID 34070214, 2021). "In breast cancer, high KRT7 gene expression was associated with a poorer prognosis." (PMID 34070214, 2021). "Colorectal cancers are typically characterized by a cytokeratin 7-negative/cytokeratin 20-positive (CK7−/CK20+) profile in 65.8% of cases, whereas primary breast cancers predominantly exhibit a CK7-positive/CK20-negative (CK7+/CK20-) pattern." (PMID 41458856, 2025). "MPD is distinguished by Paget cells within the nipple epidermis, frequently confirmed by markers such as cytokeratin 7 (CK7) and mucin 1 (MUC1), reflecting its breast cancer association." (PMID 40230781, 2025). "Samples were available from all 6 patients (five baseline, six surgery; five paired) and were stained to detect cytokeratin 7 to determine breast cancer cells, PD-L1 expression, and changes in CD8 effector T cells recruited by the combined immunotherapy." (PMID 37621406, 2023). "METTL3 promotes breast cancer lung metastasis by enhancing the stability of a keratin 7 (KRT7)-AS/KRT7 mRNA duplex and translation of KRT7." (PMID 39872957, 2023). "Studies have shown that keratin 7 (KRT7) is a key effector of m6A-induced lung metastasis of breast cancer, which promotes metastasis by increasing the stability of a KRT7-AS/KRT7 mRNA duplex and translation of KRT7." (PMID 38077434, 2023). "FTO also promotes EMT and breast cancer lung metastasis by regulating the translational extension of KRT7 mRNA via YTHDF1/eEF-1." (PMID 36358640, 2022). "No previous reports have documented neuroendocrine differentiation or cytokeratin 7 expression in isolated orbital metastases from breast cancer." (PMID 33692758, 2021). "The presence of human breast cancer cells in mouse lungs was confirmed by human cytokeratin 7 immunoreactivity." (PMID 27917859, 2016). "As expected, epithelial genes known to be inactivated during EMT in breast cancer cells, such as Cdh1 (E-cadherin), Ocln (Occludin), Epcam, Cldn7 (Claudin 7), Id1, Krt7, Esr1, Cav2, Dsp, Gata3, and Cadm1 were among the downregulated genes." (PMID 25674539, 2015). "While cytokeratin 7 is diffusely and strongly positive in breast cancer, in most gastric carcinomas its reaction is focal and heterogeneous." (PMID 25400965, 2014). "Interestingly, this analysis revealed a subset of genes that were common DEGs across multiple datasets, such as KRT7 in both ovarian and breast cancers." (PMID 40988561, 2026). "Surprisingly, we found CD24+ circulating cells (CCs) in peripheral blood of breast cancer patients which have no epithelial markers (EpCAM and cytokeratin 7/8) but was strongly associated with distant metastasis." (PMID 38806508, 2024). "However, the investigation of these epithelial markers proved ineffective in identifying cell population expressing different combinations of EpCAM and cytokeratin 7/8 with prognostic significance for breast cancer metastases." (PMID 38806508, 2024). "Tumor cells found in breast cancer expressing high KRT7 and low ESR1 phenotypes may experience increased plasticity and heterogeneity." (PMID 38892065, 2024). "KRT7 is positively expressed in most epithelial cells, such as lung and breast, and it is currently mainly used in the diagnosis and differential diagnosis of breast cancer, lung cancer and gastrointestinal adenocarcinoma." (PMID 37371833, 2023).
breast carcinoma (continued). "Breast cancer is typically cytokeratin 7-positive and cytokeratin 20-negative." (PMID 34410532, 2021). "Likewise, cytokeratin 7 is highly sensitive for breast cancer but is expressed in many epithelial tissues." (PMID 23984147, 2013). "Metastatic breast carcinomas are often positive for Cytokeratin 7(CK7), GCDFP-15, ER and/or PgR." (PMID 16854225, 2006). "Specifically, the combined expression patterns of KDM7A-DT, KRT7, and GATA3 emerge as a promising three-gene prognostic signature for breast cancer." (PMID 38756663, 2024). "Some immunohistochemical marker of EMPD are also positive in specific type of breast cancer such as human epidermal growth factor receptor 2 (Her2/erbB2), carcinoembryonic antigen (CEA), cytokeratin 7 (CK7) and gross cystic disease fluid protein 15 (GCDFP15)." (PMID 30458743, 2018). "We identified four genes that were overexpressed in cluster 2 cells—KRT7, NOTCH3, CD146, and YAP1—and analyzed publicly available expression data to assess the relevance of these genes in breast cancer." (PMID 29606612, 2018). "For instance, higher cytokeratin-7 (CK7) and epidermal growth factor receptor (EGFR) expressions (4- to 8-fold) in cancer cells have been found in lung and breast cancer patients, whereas normal leukocytes are present in a very low level of expressions." (PMID 28645267, 2017). "Cytokeratin 7, estrogen receptors, and GATA3 immunohistochemistry disclosed the presence of numerous metastatic breast carcinoma cells infiltrating the splenic parenchyma." (PMID 27672468, 2016). "We used primers for the gene sequences of UBB, ESR1 (for luminal or ER/PR+ cancer cells), HER2 and GRB7 (for HER2+ cancer cells), EPCAM, KRT7, KRT8, KRT18, and KRT19, all of which have been commonly discussed for the purpose of breast cancer diagnosis." (PMID 28936247, 2015). "In our case, all four antibodies supporting breast carcinoma, namely, estrogen and progesterone receptors, GATA 3, and cytokeratin 7, strongly reacted with the cancer cells while the benign gastric cells were negative for all of them." (PMID 25400965, 2014). "Moreover, METTL3 methylates KRT7-AS to enhance the mRNA stability of keratin 7 (KRT7) depending on IGF2BP1-modified m6A, promoting breast cancer lung metastasis." (PMID 35541906, 2022). "Histopathological examination of the breast cancer showed it to be cytokeratin 7-negative invasive ductal carcinoma with neuroendocrine differentiation." (PMID 33692758, 2021). "While markers usually positive in gastric adenocarcinoma such as cytokeratin 20, CDX2, MUC5AC, and Hep Par 1 were negative, those supporting breast carcinoma (estrogen and progesterone receptors, cytokeratin 7, and GATA3) decorated the cancer cells." (PMID 25400965, 2014). "Cytokeratin 7 (CK-7) is positive for most breast cancers but negative for colon cancer." (PMID 36451153, 2022). "Immunohistochemistry confirmed positive for cytokeratin 7(CK7), GATA-3 and GCDFP15, as well as negative staining of cytokeratin 20 (CK20), suggesting breast cancer metastasis." (PMID 38500767, 2024). "Cytokeratin 7 (CK7) and GATA binding protein 3 (GATA3) are considered as immunohistochemical hallmarks of breast cancers; however, there are breast tumors lacking these markers." (PMID 31718619, 2019). "MYC and MAX RNA were detected in circulating breast cancer monocytes (KRT7+, CD11b+, CSF1R+), whole breast cancer tissue (KRT7+, CD11b+, CSF1R+), and isolated breast cancer tumor infiltrating macrophages (KRT7 negative or low, CD11b+, CSF1R+), supporting a potential role for MYC in human TAMs." (PMID 32685002, 2020).
lung adenocarcinoma (93 papers, 2002 to 2026). A carcinoma that arises from the lung and is characterized by the presence of malignant glandular epithelial cells. "Cytokeratin 7 is an intermediate filament protein found in epithelial lung cells, commonly associated with lung adenocarcinoma." (PMID 39070460, 2024). "Elevated KRT7 mRNA was also significantly associated with poorer outcomes in the intestinal subtype of gastric carcinoma and in lung adenocarcinoma, the most common subtype of non-small-cell lung cancer." (PMID 34070214, 2021). "Other main biomarkers of lung adenocarcinoma such as cytokeratin 7 (CK7) and mucin-1 (MUC1) were also assessed by IHC on PDTs and PDHOs." (PMID 38698850, 2024). "Lung adenocarcinomas express cytokeratin 7 (CK7) and in most cases thyroid transcription factor-1 (TTF-1), where the latter is considered lineage-specific as it is essentially not expressed in squamous cell carcinoma." (PMID 39441367, 2024). "The present study aimed to investigate the potential impact of KRT7 mRNA expression on the treatment response and prognosis of patients with advanced lung adenocarcinoma who underwent first-line platinum-based chemotherapy." (PMID 38260844, 2023). "For instance, acinar or large glandular structures were observed in lung adenocarcinoma organoids along with the expression of tumor markers, including napsin-A and cytokeratin 7 (CK7)." (PMID 35551634, 2022). "Primary and subcutaneous tumors express cytokeratin-7 and thyroid transcription factor-1, markers characteristic to lung adenocarcinoma." (PMID 29415661, 2018). "In addition, immunohistochemistry staining of the eyelid biopsy was negative for thyroid transcription factor 1 (TTF-1), a marker for lung adenocarcinoma, and positive for cytokeratin 7 (CK-7), which is typical of adenocarcinoma of the adnexal system." (PMID 40160875, 2025). "We performed immunohistochemistry to detect Keratin 7, a protein mainly expressed in epithelial cells and highly expressed in lung adenocarcinoma, thus to determine whether the lymphadenectasis was a result of tumor metastasis." (PMID 37919290, 2023). "Moreover, bioinformatics analysis of datasets in lung adenocarcinoma identifies the correlation of SLFN12 with other known lung adenocarcinoma markers like KRT7, Napsin A, and TTF-1." (PMID 32987632, 2020). "Immunohistochemical staining was positive for thyroid transcription factor 1 (TTF-1), cytokeratin 7 (CK7) and mucin 1 cell surface associated (MUC1), while negative for cytokeratin 20 (CK20), and CD15, thus suggesting bladder metastasis from lung adenocarcinoma." (PMID 24716732, 2014). "Immunohistochemistry was positive for CKAE1/3, Cytokeratin 7 (CK7), thyroid transcription factor 1 (TTF-1), and Napsin A, supporting a diagnosis of lung adenocarcinoma." (PMID 40821300, 2025). "Biopsy results of the lung mass were positive for cytokeratin 7 and TTF-1, markers that are highly specific for adenocarcinoma of the lung." (PMID 39070460, 2024). "The expression patterns of lung adenocarcinoma (LUAD) markers, such as thyroid transcription factor-1 (TTF-1), cytokeratin 7 (CK7), and napsin A, were maintained in PDO." (PMID 37993887, 2023). "TTF1, KRT7, SOX2, P63, and KRT5 are biomarkers for poor prognosis of lung adenocarcinoma and lung squamous cell carcinoma." (PMID 38248716, 2023). "Right upper lung CT-guided biopsy revealed moderately differentiated adenocarcinoma with immunohistochemical (IHC) staining positive for cytokeratin 7 and thyroid transcription factor and negative for cytokeratin 20, consistent with lung adenocarcinoma." (PMID 39637337, 2024). "A core biopsy specimen of the left lower lobe mass showed lung adenocarcinoma that was positive for cytokeratin 7 (CK7), negative for cytokeratin 20 (CK20), and positive for thyroid transcription factor 1 on immunoperoxidase staining." (PMID 34398022, 2021).
lung adenocarcinoma (continued). "The lung adenocarcinoma metastasis was composed of solid groups of tumor cells without any glandular formations and displayed cytokeratin 7 and thyroid transcription factor 1 (TTF-1) immunopositivity." (PMID 34514560, 2021). "Positive staining for Keratin 7, TTF1, or Napsin A can indicate lung adenocarcinoma." (PMID 25955027, 2015). "We used real-time reverse transcription PCR (RT-PCR) to detect survivin, human telomerase reverse transcriptase (hTERT), cytokeratin-7 (CK-7) and thyroid transcription factor 1 (TTF-1) mRNA expression levels in 68 advanced lung adenocarcinoma patients and 30 healthy patients." (PMID 23599802, 2013). "Immunohistologically, the tumor cells were stained positive for cytokeratin 7 (CK7) in the cytoplasm and for thyroid transcription factor 1 (TTF-1) in the nucleus, but negative for cytokeratin 20 (CK20), suggesting that the tumor cells originated from either thyroid cancer or lung adenocarcinoma." (PMID 18801198, 2008). "Immunohistochemical staining showed that the tumor cells were positive for thyroid transcription factor‐1 (TTF‐1) and keratin 7 (K7) but negative for keratin 20 (K20) and prostate‐specific antigen (Figure not shown), which supported the diagnosis of poorly differentiated lung adenocarcinoma." (PMID 40309045, 2026). "Previous work has shown that cytokeratins 7 and 8 (KRT7 and KRT8) can be targeted in lung adenocarcinomas, while white blood cells should have no cytokeratin expression." (PMID 29186152, 2017). "Immunostaining of tumor cells were positive for thyroid transcription factor‐1 (TTF‐1) and cytokeratin 7 (CK7), while negative for caudal‐related homeobox transcription factor 2 (CDX‐2) and cytokeratin 20 (CK‐20), indicating a lung adenocarcinoma origin." (PMID 28781870, 2017).
colorectal cancer (90 papers, 2002 to 2026). A primary or metastatic malignant neoplasm that affects the colon or rectum. "Other published works have indicated that elevated KRT7 is also associated with an unfavourable outcome in pancreatic cancer, esophageal squamous cell carcinoma and colorectal carcinoma." (PMID 34070214, 2021). "KRT7 expression is associated with a higher morbidity and a higher progression in colorectal cancer." (PMID 29868478, 2018). "Landau and coworkers provided evidence that CDX2 loss was observed not only in MSI-H BRAF-mutated colorectal cancers, but also in a subgroup of MSS BRAF-mutated colorectal cancers, characterized by an aggressive clinical phenotype and increased Cytokeratin 7 expression expression." (PMID 29652830, 2018). "KRT7 displayed atypical expression in different types of cancers like esophageal squamous cell carcinoma and colorectal cancer." (PMID 38893622, 2024). "KRT7 was reported as a predictive factor of various types of cancer, such as colorectal cancer and renal clear cell carcinoma, but bad prognostic factor in esophageal squamous cell carcinoma and pancreatic adenocarcinoma." (PMID 34422643, 2021). "Previous study indicated that KRT7 showed enhanced expression levels in several cancer types, such as colorectal carcinoma, esophageal squamous cell carcinoma and gastric cancer, and associates with metastasis." (PMID 33708105, 2020). "Both lung and upper gastrointestinal tract (stomach, pancreas) often express cytokeratin 7 while colorectal carcinomas are less likely to be positive." (PMID 23119210, 2012). "Body mass index, carcinoembryonic antigen (CEA), carbohydrate antigen 19-9, tumor marker CA72-4 (CA72-4), cytokeratin-7 (CK-7), CTC count, and neutrophil-to-lymphocyte ratio (P < .2) are risk factors for liver metastasis after radical resection of colorectal cancer." (PMID 39792713, 2025). "Keratin 7-negative and keratin 20-positive phenotypes were typical for colorectal carcinomas, although the loss of CDX-2 expression was noted in some colon rhabdoid carcinomas." (PMID 36732357, 2023). "In conclusion, our study provides interesting results indicating that cytokeratin 7 in colorectal carcinoma is an independent marker of a poor prognosis, which may be regarded as unexpected in context of several previously published studies that examined the same question." (PMID 34504224, 2021). "Keratin 7 (KRT7), as a member of the keratin gene family, is abnormally expressed in different types of malignant tumours, such as esophageal squamous cell carcinoma, colorectal cancer and ovarian cancer." (PMID 37815881, 2023). "In colorectal cancer, KRT7 is usually not expressed in the normal colonic epithelium or localized colorectal cancer (using the same OV-TL 12/30 antibody) but was found in some lymph node metastatic cells." (PMID 35406395, 2022). "The right ovarian tumor proved to be moderately differentiated adenocarcinoma that was positive for cytokeratin 20 and negative for cytokeratin 7 staining, indicating metastasis from the colorectal cancer." (PMID 30094696, 2018).